SALL4 (spalt like transcription factor 4)
Diseases named in the same sentence as SALL4 in open-access papers (continued):
Sharing a sentence is not in itself a finding about the gene and the disease.
gastric cancer (continued). "The results of rescue study revealed that CD44 overexpression antagonized SALL4 knockdown-mediated inhibition of gastric cancer cell proliferation, migration, and invasion in vitro and gastric cancer growth in vivo." (PMID 27819668, 2016). "We further confirmed the inhibitory effect of SALL4 knockdown on the growth of gastric cancer cells by using cell colony formation assay." (PMID 27819668, 2016). "Although miR-497 suppresses GC tumorigenesis and progression, it is still unknown whether SALL4 participates in the regulation of miR-497 in gastric cancer." (PMID 38584262, 2024). "Furthermore, the negative correlation of PTGDR2 with mRNA expression of OCT4, NANOG, LGR5, and SALL4 in cancerous tissues also demonstrated the relevance of these in vitro results to gastric cancer." (PMID 38704736, 2024). "Overexpression of SALL4 has been reported in a variety of cancers including gastric cancer." (PMID 37525212, 2023). "Here, we investigated the potential role of SALL4 in gastric cancer angiogenesis." (PMID 37525212, 2023). "In addition, SALL4 bound to the CD44 promoter region and activated its transcription, and CD44 overexpression reversed the inhibition of gastric cancer cell proliferation, migration, and invasion caused by SALL4 knockdown." (PMID 37525212, 2023). "Furthermore, we used exosomes as a nanocarrier vesicle to deliver SALL4-B-targeting siRNA and the chemotherapeutic drug thalidomide for the suppression of gastric cancer angiogenesis by inhibiting the SALL4/VEGF pathway." (PMID 37525212, 2023). "We also applied thalidomide in our study to inhibit the activation of SALL4 and tested whether this treatment will affect gastric cancer angiogenesis through modulating VEGF gene expression." (PMID 37525212, 2023). "Thus, our findings suggest that SALL4 is critically involved in gastric cancer progression by regulating VEGF and angiogenesis, thus providing a potential target for cancer therapy." (PMID 37525212, 2023). "Noteworthily, most of the other microRNA/SALL4 interactions are only supported by individual publications and await further validation, except for miR-219 which has also been shown to regulate SALL4 in colon cancer, and miR-16 in gastric cancer in addition to glioma." (PMID 34573282, 2021). "In addition, SALL4 knockdown downregulates the expression of a multifunctional transmembrane glycoprotein CD44 in gastric cancer and lung adenocarcinoma cells." (PMID 34441397, 2021). "Therefore, we recommend using sAFP and AFP/GPC3/SALL4 immunohistochemistry for all cases of gastric cancer." (PMID 34706681, 2021). "Prostaglandin D2 (PGD2) synthase (PTGDS) and its receptor PTGDR2 are negatively correlated with stem genes (Sall4 and Lgr5) in gastric cancer, which restricts tumor self-renewal, growth, and metastasis by relying on the PTGDR2 pathway to inhibit STAT3 phosphorylation and nuclear expression." (PMID 33312950, 2020). "We first wanted to know whether SALL4 modulates the glycolytic phenotype of cultured gastric cancer cells." (PMID 32489324, 2020). "Taken together, these findings indicate that SALL4 regulates glycolysis in gastric cancer cells." (PMID 32489324, 2020). "Our results suggest that SALL4 could promote gastric cancer progression through HK-2-mediated glycolysis, which represents a new mechanism for the oncogenic roles of SALL4 in cancer." (PMID 32489324, 2020). "Moreover, HK-2 knockdown reversed the promoting role of SALL4 in gastric cancer cell proliferation, migration and invasion, suggesting that SALL4 drives gastric cancer progression by upregulating HK-2." (PMID 32489324, 2020). "In this study, we found that SALL4 could also regulate the transcription of HK-2, thereby promoting glycolysis and gastric cancer progression." (PMID 32489324, 2020). "The gastric cancer cells with high levels of SALL4 seem to also have increased expression of HK-2." (PMID 32489324, 2020).
gastric cancer (continued). "SALL4 could enhance the proliferation, migration and invasion of gastric cancer cells by regulating CD44, DANCR, and TGF-β1 expression." (PMID 32489324, 2020). "Therefore, SALL4 likely promotes gastric cancer progression, at least in part, by directly activating CD44 expression." (PMID 29747682, 2018). "These gastric cancers similarly exhibited the expression of Sall4 and Lin28a." (PMID 29802314, 2018). "Furthermore, SALL4 upregulation plays crucial roles in carcinogenesis in gliomas and gastric cancers." (PMID 29228922, 2017). "Our data also showed that there was a positive correlation between IL-17RB and Oct4, Nanog, Lgr5, or Sall4 mRNA expression, and that the expression of Oct4, Sox2, and Sall4 proteins increased in proportion to the increased expression of IL-17RB in gastric cancer tissues." (PMID 27146881, 2016). "We examined the role of SALL4 knockdown in gastric cancer cell growth by using cell counting assay." (PMID 27819668, 2016). "SALL4 knockdown greatly retarded the growth of gastric cancer cells." (PMID 27819668, 2016). "SALL4 knockdown greatly reduced the migration and invasion abilities of gastric cancer cells." (PMID 27819668, 2016). "Inducible knockdown of SALL4 inhibits the proliferation and migration of gastric cancer cells." (PMID 27819668, 2016). "Moreover, overexpression of CD44 in SALL4 knockdown cells led to increased gastric cancer cell proliferation, migration and invasion in vitro as well as increased tumour growth in mouse models." (PMID 27819668, 2016). "We then checked the effects of SALL4 knockdown on the malignant phenotypes of gastric cancer cells." (PMID 27819668, 2016). "Similarly, Tet-induced knockdown of SALL4 suppressed the motility and migration abilities of gastric cancer cells." (PMID 27819668, 2016). "We next detected the effects of SALL4 knockdown on the motility of gastric cancer cells." (PMID 27819668, 2016). "ChIP studies showed that the endogenous SALL4 protein could bind to the specific promoter region of CD44 in gastric cancer cells, suggesting that CD44 is a direct target of SALL4." (PMID 27819668, 2016). "We also observed that SALL4 knockdown sensitized gastric cancer cells to cisplatin treatment." (PMID 27819668, 2016). "In particular, we identified CD44 as a downstream target of SALL4 in gastric cancer cells." (PMID 27819668, 2016). "First, since SALL4 is expressed in solid tumors such as germ cell tumors (GCTs), gastric cancer, and breast cancer in addition to AML, we hypothesized that SALL4 can confer a general drug resistant phenotype." (PMID 21526180, 2011). "In addition to AML, SALL4 has been reported to be expressed in solid tumors such as germ cell tumors (GCTs), gastric cancer, and breast cancer." (PMID 21526180, 2011). "Furthermore, the CM from thalidomide-treated gastric cancer cells displayed an impaired effect to promote the proliferation, migration, and tube formation of HUVECs, indicating that thalidomide may target SALL4 to inhibit VEGF signaling." (PMID 37525212, 2023). "Hence, SALL4 knockout greatly attenuates gastric cancer angiogenesis in vitro." (PMID 37525212, 2023). "SALL4, a transcriptional factor involved in embryonic stem cell self-renewal and pluripotency, is overexpressed in gastric cancer (GC)." (PMID 33644042, 2021). "To verify whether the regulation of HK-2 by SALL4 is critical for gastric carcinogenesis, we established subcutaneous tumor-bearing and peritoneal metastasis tumor mouse models by using control and SALL4 knockdown gastric cancer cells." (PMID 32489324, 2020). "Therefore, SALL4 may maintain the malignant phenotypes of gastric cancer cells by regulating HK-2-mediated glycolysis." (PMID 32489324, 2020).
gastric cancer (continued). "Considering that HK-2 is the first rate-limiting enzyme of glycolysis and it showed the most significant change after SALL4 knockdown and overexpression in gastric cancer cells, we hypothesized that SALL4 might promote glycolysis through the regulation of HK-2 in gastric cancer cells." (PMID 32489324, 2020). "To clarify whether there was a relationship between the expression of IL-17RB and stemness in gastric cancer tissues, we first detected the expression of Oct4, Nanog, Lgr5, and Sall4 mRNA using real-time quantitative PCR, and analyzed the relationship between them and IL-17RB mRNA." (PMID 27146881, 2016). "Considering the critical role of SALL4 in cancer angiogenesis by regulating VEGF, we wanted to target SALL4 for gastric cancer therapy by using an exosome-mediated drug delivery approach." (PMID 37525212, 2023). "Beforehand, it has been studied that SALL4 is involved in the EMT process in several types of cancer, including BC, gastric cancer, endometrial cancer, colorectal cancer and esophageal squamous cell carcinoma." (PMID 36362083, 2022). "Studies have confirmed that the expression of SALL4 and CD44 is also positively correlated in gastric cancer cells." (PMID 36316684, 2022). "However, SALL4 was found to be overexpressed in various tumors, such as gastric cancer (GC), lung cancer, endometrial cancer, hepatocellular carcinoma (HCC), and acute myeloid leukemia (AML)." (PMID 35216168, 2022). "SALL4 induces EMT by activating TGF-β/SMAD signaling pathway and promotes gastric cancer metastasis." (PMID 35692499, 2022). "We also found that stable and inducible knockdown of SALL4 upregulated the expression of E-cadherin, which is in support of the finding that SALL4 promotes EMT in gastric cancer cells." (PMID 27819668, 2016). "Our findings indicate that SALL4 promotes gastric cancer growth and metastasis through the activation of CD44, which represents a new mechanism responsible for the oncogenic roles of SALL4 in cancer." (PMID 27819668, 2016). "The results of western blot showed that the expression of CD44, SALL4, c-MYC, Oct4, Nanog, and Sox2 proteins also increased in 1 μM and 10 μM DIM-treated gastric cancer cells." (PMID 26918831, 2016). "We also found a positive correlation between SALL4 and CD44 expression in gastric cancer cell lines and gastric cancer tissues, further supporting the regulation of CD44 by SALL4." (PMID 27819668, 2016). "Aberrant SALL4 expression has been reported in acute myeloid leukemia (AML) and a panel of solid tumors, including hepatocellular carcinoma (HCC), gastric cancer, and endometrial cancer." (PMID 27705911, 2016). "Clinical studies demonstrated that the expression of SALL4 and CD44 was positively correlated in gastric cancer patient samples." (PMID 27819668, 2016). "Besides, positivity of SALL4 can aid in the diagnosis of hepatoid adenocarcinoma of stomach (HAS), a special subtype of gastric cancer with poor prognosis." (PMID 38584262, 2024). "SALL4 knockdown downregulates the expression of stemness- and EMT-related genes (OCT4, SOX2, NANOG, C-MYC and CD44) and suppresses the activation of the ERK, STAT3 and NF-κB pathways, thus inhibiting the proliferation and migration of gastric cancer cells." (PMID 38584262, 2024). "Also, SALL4 bound to the TGF-β1 promoter and promoted gastric cancer metastasis by upregulating TGF-β1 and activating the SMAD signaling pathway." (PMID 37525212, 2023). "Given the potential role of SALL4 in regulating VEGF gene expression, we sought to investigate whether SALL4 modulates angiogenesis in gastric cancer." (PMID 37525212, 2023). "In conclusion, our study suggests that SALL4 plays a critical role in gastric cancer angiogenesis by modulating VEGF expression, and targeting SALL4 may be an effective strategy for anti-angiogenic therapy of gastric cancer." (PMID 37525212, 2023). "It was suggested that in gastric cancer cells, DANCR could be activated by SALL4, which could bind to the promoter of DANCR." (PMID 34722539, 2021).
gastric cancer (continued). "Furthermore, in a study of 32 cases of AFP-producing gastric cancer, only 16% were positive for diffuse staining (50% or more of tumor cells) in AFP, whereas it was as high as 56% positive for glypican-3 and 78% for SALL4." (PMID 34792649, 2021). "Notably, as observed in gastric cancers in KC-OSKM mice, SALL4, LIN28A, and LIN28B were frequently co-expressed in human AFP-producing gastric cancers, suggesting that these cancers exhibit activation of the pluripotency-related regulatory network." (PMID 29802314, 2018). "For example, miR-219-5p inhibited the growth and metastasis of gastric cancer cells via targeting LRH-1, and miR-219-5p exerted a antitumor function in colon cancer via binding to Sall4; however, the expression and effect of miR-219-5p in melanoma still remained unclear." (PMID 28884131, 2017). "AFP-producing gastric cancer highly expresses VEGF-C, SALL4, and c-Met/HGF." (PMID 27995033, 2016). "Aberrant SALL4 expression has been reported in a myriad of solid tumors including HCC, endometrial cancer, ovarian cancer, breast cancer, gastric cancer, lung cancer, and germ cell tumors, as well as in leukemias." (PMID 27705911, 2016). "To further clarify the importance of SALL4-mediated upregulation of CD44 in gastric cancer growth in vivo, we implanted SALL4 knockdown cells with or without CD44 overexpression into the nude mice." (PMID 27819668, 2016). "SALL4 knockdown greatly inhibited the expression of phosphorylated ERK, STAT3 and NF-κB, suggesting an important role of SALL4 in modulating the activation of these pathways in gastric cancer cells." (PMID 27819668, 2016). "Collectively, our findings indicate that SALL4 promotes gastric cancer progression through directly activating CD44 expression, which suggests a novel mechanism for the oncogenic roles of SALL4 in gastric cancer and represents a new target for gastric cancer therapy." (PMID 27819668, 2016). "Collectively, these findings demonstrate a strong role for SALL4 in gastric cancer angiogenesis through modulating the VEGF family and establishing a synergistic treatment via the exosomes-nano carrier system as a promising strategy for gastric cancer treatment." (PMID 37525212, 2023). "In agreement with the previous findings, our results showed that SALL4 could bind to the (-601 to -711), (-690 to -822), (-852 to -1080) regions of the promoter of VEGF-A, B, and C genes, respectively, and activate their expression in gastric cancer cells." (PMID 37525212, 2023). "While this underscores the gene-level importance of SALL4 isoforms in cancer progression, our study is unique in evaluating the SALL4-A isoform at the protein level, particularly in gastric cancer, which may reveal distinct biological functions that are not discernible through gene silencing alone." (PMID 39905414, 2025). "However, it could not be excluded that SALL4 may regulate glycolysis and participate in gastric cancer progression through other mechanisms." (PMID 32489324, 2020). "In our study, the expression of transcription factors Oct4, Sox2, c-MYC, Nanog and SALL4 as well as the ability to differentiate into adipocytes in gastric cancer cells were enhanced by low level of DIM, suggesting that low level of DIM may affect gastric cancer cell reprogramming." (PMID 26918831, 2016).
hepatocellular carcinoma (47 papers, 2014 to 2025). A malignant tumor that arises from hepatocytes. "SALL4 is a tumor promoting gene and is associated with the progression of many cancers, such as hepatocellular carcinoma, esophageal squamous cell carcinoma, acute myeloid leukemia and endometrial cancer." (PMID 35619068, 2022). "Recent studies have implicated high expression levels of SALL4 in tumorigenesis of numerous human malignancies including acute myeloid leukemia, hepatocellular carcinoma, endometrial cancer and esophageal squamous cell carcinoma." (PMID 32513235, 2020). "Some researchers have found that SALL4 was reexpressed and associated with the poorest prognosis in a subgroup of adult hepatocellular carcinomas." (PMID 24860834, 2014). "As a consequence of its functional roles in cancer cell and absence in adult normal tissue, SALL4 is both a marker for an aggressive subtype of hepatocellular carcinoma (HCC) and a potential target to prevent the high-risk occurrence of endometrial cancer." (PMID 24860834, 2014). "SALL4 in hepatocellular carcinoma cells silences tumor suppressor genes through RBBP4/7 binding to NuRD." (PMID 38028543, 2023). "SALL4 silences the expression of tumor suppressors through NuRD, thereby promoting hepatocellular carcinoma cell survival." (PMID 38028543, 2023). "Dysregulation of SALL4 can be observed in multiple human cancer types, including germ cell tumors, leukemia, hepatocellular carcinoma (HCC), colorectal carcinoma (CRC), breast cancer, and lung cancer." (PMID 34573282, 2021). "A similar result showed that DNA methylation induces SALL4 gene repression in hepatocellular carcinoma in the case of hepatitis virus infection." (PMID 34072812, 2021). "Enhanced SALL4 expression is observed in early-stage breast cancer tissues and serum of hepatocellular carcinoma patients, suggesting a potential role for SALL4 in early cancer detection and diagnosis." (PMID 32513235, 2020). "The SALL4 complexed to RBBp4, the chaperone subunit of NuRD, causes silencing of the tumor-suppressor gene PTEN in hepatocellular carcinoma." (PMID 32575664, 2020). "Therapeutic peptides targeting SALL4 exhibit potent antitumor activity in hepatocellular carcinoma, thus establishing SALL4 as a promising drug target." (PMID 32513235, 2020). "Patients with higher SALL4 levels exhibit poorer overall survival in hepatocellular carcinoma and endometrial cancer." (PMID 32513235, 2020). "Here the authors link the zinc-finger transcription factor SALL4 with miR-200c inhibition of PD-L1 expression by hepatocytes in patients with HBV-induced hepatocellular carcinoma." (PMID 29593314, 2018). "For instance, miR-181b, miR-219, miR-98, and miR-33b have been reported to target directly SALL4, and act astumor suppressors or metastasis suppressors in glioma, hepatocellular carcinoma, and breast cancer, respectively." (PMID 30423818, 2018). "For examples, zinc finger transcription factor Sall4 controls the cell fate decision of hepatoblasts and serves as a marker for progenitor subclass of hepatocellular carcinoma." (PMID 29202695, 2017). "According to the result of gene expression analysis, the overexpression of metastatic and proliferative genes in SALL4-positive hepatocellular carcinomas enriches the progenitor-like gene." (PMID 28819584, 2017). "The aim of this study was to investigate the clinicopathologic characteristics of sal-like protein 4 (SALL4)-immunopositive hepatocellular carcinoma (HCC)." (PMID 26034695, 2014). "However, the RBBP4 subunit can also bind to SALL4 and subsequently recruit the NuRD complex to the promoters of tumor suppressors and silence their expression, thereby promoting hepatocellular carcinoma cell survival." (PMID 38028543, 2023). "NuRD complex interacts with SALL4 to regulate stemness of EpCAM-positive hepatocellular carcinoma." (PMID 37880213, 2023). "In addition, miR-296-5p exerts an inhibitory effect on stemness potency of hepatocellular carcinoma cells via Brg1/Sall4 axis." (PMID 35590240, 2022).